CCR9 (C-C motif chemokine receptor 9)
Diseases named in the same sentence as CCR9 in open-access papers (continued):
Sharing a sentence is not in itself a finding about the gene and the disease.
lung adenocarcinoma (continued). "We assessed the correlation of CCR9 expression with clinicopathological characteristics and the prognosis of lung adenocarcinoma." (PMID 26168791, 2015). "CCR9 expression at the protein level was examined by immunohistochemistry on 144 lung adenocarcinoma tissues and 30 adjacent normal lung tissues (used as normal controls)." (PMID 26168791, 2015). "In addition, these findings support the possible use of CCR9 as a novel target for the treatment of lung adenocarcinoma." (PMID 35163455, 2022). "Our findings provided evidence that CCR9/CCL25 could be used as novel therapeutic targets for lung adenocarcinoma." (PMID 32308544, 2020). "However, little is known about the effect and mechanism of CCR9 on distant metastasis in lung adenocarcinoma." (PMID 32308544, 2020). "A future study will investigate whether CCR9 can act as a new therapeutic target in lung adenocarcinoma." (PMID 26168791, 2015). "Nevertheless, it remains elusive whether these findings of CCR9 can be extended to lung adenocarcinoma patients." (PMID 26168791, 2015). "Therefore, over-expression of CCR9 in lung adenocarcinoma suggested its crucial role in disseminating primary tumor and promoting tumor cell survival during metastasis." (PMID 26168791, 2015). "We, for the first time, reported that CCR9 could be beneficial in predicting lymph node metastasis, and it might act as a novel prognostic biomarker for lung adenocarcinoma." (PMID 26168791, 2015). "The expression of CCR9 was significantly increased in lung adenocarcinoma tissue." (PMID 26168791, 2015). "Moreover, higher expression of CCR9 in lung adenocarcinoma was significantly correlated with advanced TNM stage (p = 0.012)." (PMID 26168791, 2015). "However, the effect and mechanisms of CCR9 on lung adenocarcinoma distant metastasis remain largely unknown." (PMID 32308544, 2020). "Furthermore, after adjustment of lymph node status, TNM stage and chemotherapy, multivariate analysis revealed that CCR9 expression could be used as an independent factor for predicting post-operation survival in patients with lung adenocarcinoma." (PMID 26168791, 2015). "MMP-2 exhibits greater reactivity to CCL25 in lung adenocarcinoma compared to lung SCC, likely due to differential MMP activity and CCR9 phosphorylation." (PMID 40607416, 2025). "The expression of CCR9 and its ligand CCL25 in the tumor tissues of lung adenocarcinoma patients was investigated using immunohistochemistry." (PMID 32308544, 2020). "No studies have examined the expression profiles of CCR9 in lung adenocarcinoma patients with curative resection and its effect on lung adenocarcinoma survival." (PMID 26168791, 2015).
myocardial infarction (5 papers, 2016 to 2023). Gross necrosis of the myocardium, as a result of interruption of the blood supply to the area, as in coronary thrombosis. "The CCR9 was previously reported to be related to the process of inflammatory expression and myocardial remodeling after myocardial infarction." (PMID 36064568, 2022). "In CCR9 knockout CCR9+/+ mice, surgical ligation of the left anterior descending coronary artery caused myocardial infarction (MI), and found that the expression of CCR9 in the heart of mice was significantly up-regulated after MI." (PMID 34490243, 2021). "Our previous investigation found that severe inflammatory response and myocardial fibrosis occurred after myocardial infarction, and CCR9 gene knockout can alleviate inflammation and myocardial fibrosis." (PMID 34712704, 2021). "However, the role of CCR9 in the pathological process of myocardial infarction (MI) remains unexplored; inflammation plays a key role in this process." (PMID 27585634, 2016). "Down-regulation of CCR9 expression can improve survival rate, left ventricular dysfunction, cardiac function, reduce infarct size, meanwhile, significantly attenuate the apoptosis of cardiomyocytes, and inhibit the inflammatory response after myocardial infarction." (PMID 34490243, 2021). "CCR9/CCL25 axis may play an important role in inflammatory cell infiltration and cardiac remodeling after myocardial infarction." (PMID 34490243, 2021).
respiratory failure (5 papers, 2021 to 2025). The significant impairment of gas exchange within the lungs resulting in hypoxia, hypercarbia, or both, to the extent that organ tissue perfusion is severely compromised. "Different human polymorphisms have an impact on clinical outcomes: sequence changes in ApoE, TLR7, TMEM189-UBE2V1, as well as SLC6A20, LZTFL1, CCR9, FYCO1, CXCR6, XCR1, have been associated with severe disease outcomes as well as respiratory failure." (PMID 35207458, 2022).
celiac disease (4 papers, 2010 to 2024). An autoimmune genetic disorder with an unknown pattern of inheritance that primarily affects the digestive tract. "We found 54 single-nucleotide polymorphisms (SNPs) in 5 genes associated with celiac disease (TAGAP, IL18R1, RGS21, PLEK, and CCR9) in time to celiac disease analyses (10−4>P>5.8x10−6)." (PMID 27015091, 2016). "On the other hand, association evidence for RGS21, IL18R1, PLEK, CCR9, TAGAP was only found for celiac disease." (PMID 27015091, 2016). "However, confirmatory evidence (p<10−4) was found for SNPs in five regions previously reported to be associated with celiac disease (TAGAP, IL18R1, RGS21, PLEK, and CCR9)." (PMID 27015091, 2016). "In peripheral blood, CD38 expression on pre-activated CD62Llow CD4+ T cells correlates with CCR9 and particularly with β7-integrin expression, and gliadin-specific CD4+ T cells from patients with celiac disease are homogenously CD38+." (PMID 25938500, 2015).
Chronic colitis (4 papers, 2011 to 2025). A chronic inflammatory disease of the large intestine (colon, cecum and rectum). "A higher CCR9 expression in D3R-deficient Treg cells from the mesenteric lymph nodes of mice with chronic colitis was also observed." (PMID 34884737, 2021). "CCR9/CCL25 interactions have protection against large intestinal inflammation in chronic colitis." (PMID 34490243, 2021). "Further investigation will determine whether CCL25/CCR9 interactions play a role in DSS chronic colitis." (PMID 21283540, 2011).
colorectal cancer (4 papers, 2017 to 2025). A primary or metastatic malignant neoplasm that affects the colon or rectum. "Our results reveal that CCR9 controls the immune microenvironment of colorectal cancer differentially affecting both CD8+ T cells and Tregs, and that its absence results in an increase in the CD8+/Treg cell ratio, which promotes an enhanced anti-tumoral response." (PMID 40305493, 2025). "In addition, we suggest a novel potential immune surveillance evasion mechanism through which colorectal carcinoma tissue perturbs the ability of CCR9+ T lymphocytes to be recruited to the tumor." (PMID 29020986, 2017).
liver fibrosis (4 papers, 2019 to 2025). "Blocking the CCR9/CCL25 axis with a CCR9 antagonist represents an effective approach to mitigate the progression of hepatic fibrosis." (PMID 40977736, 2025). "Recently, we reported that inhibition of the CCR9/CCL25 axis ameliorates acute hepatitis and liver fibrosis via regulation of hepatic macrophages." (PMID 35943802, 2022).
non-small cell lung carcinoma (4 papers, 2014 to 2025). A group of at least three distinct histological types of lung cancer, including non-small cell squamous cell carcinoma, adenocarcinoma, and large cell carcinoma. "In this study, we for the first time show the clinical and biological significance of CC chemokine receptor-9 (CCR9) in non-small cell lung cancer (NSCLC)." (PMID 25296976, 2014). "In this study for the first time we have shown the potential role of CCR9 in LuCa, which was highly expressed in non-small cell lung carcinoma (NSCLC) tissues compared to controls." (PMID 25296976, 2014). "Chemokine receptors such as CCR9 and CCR10 have also been identified as potential biomarkers in non-small cell lung cancer (NSCLC)." (PMID 41149503, 2025).
Acute hepatitis (3 papers, 2012 to 2022). Acute hepatic injury resulting from inflammation typically accompanied by increased serum alanine transaminase activity. "With regard to liver immunology, CCR9+ macrophages play a pathogenic role in a murine acute hepatitis model and humans." (PMID 35744024, 2022). "Peripheral blood samples from patients with acute hepatitis had more TNF-α-producing CCR9+ monocytes than healthy volunteers." (PMID 35744024, 2022). "In turn, acute hepatitis was largely prevented in CCR9−/− animals and severe inflammation could be restored by adoptive transfer of macrophages from CCR9+/+ mice." (PMID 23091461, 2012).
cardiac hypertrophy (3 papers, 2016 to 2024). "CCR9 is also associated with cardiac hypertrophy in mice models." (PMID 38247848, 2024). "They found that overexpression of CCR9 exacerbated pressure overload–induced cardiac hypertrophy and dysfunction." (PMID 27585634, 2016).
food allergy (3 papers, 2020 to 2024). Gastrointestinal disturbances, skin eruptions, or shock due to allergic reactions to allergens in food. "In the same line, the CCR9:DRD5 heteromer seems to be exclusively involved in the infiltration of CD4+ T-cells in the colonic mucosa upon inflammation, and not in homeostatic conditions, as Drd5−/− mice do not develop issues associated with food allergy." (PMID 39337509, 2024).
hepatocellular carcinoma (3 papers, 2015 to 2022). A malignant tumor that arises from hepatocytes. "It has been demonstrated that IIN concerning IgA production is involved in some types of cancer, such as hepatocellular carcinoma, which can be activated by CCR9, CCR10, and CXCR4 to promote tumor growth and metastases." (PMID 35883015, 2022). "Additionally, the ectopic expression of CCR9 has been shown to be an independent prognostic factor for the overall survival of hepatocellular carcinoma patients." (PMID 26879872, 2016). "Studies have revealed that ectopic expression of CCR9 may be mediated by the downregulation of p21 and p27 and upregulation of cyclin D1 to enhance cell proliferation and tumorigenicity in hepatocellular carcinoma cells." (PMID 26879872, 2016). "Therefore, CCR9 expression can act as a novel prognostic marker and therapeutic target for hepatocellular carcinoma and may be a useful biological marker of the clinical efficacy of infliximab therapy in psoriasis patients." (PMID 26879872, 2016).
T-cell acute lymphoblastic leukemia (3 papers, 2018 to 2023). Acute lymphoblastic leukemia of T-cell origin. "Moreover, CCR9 is highly expressed in tumors, including several solid tumors and T-cell acute lymphoblastic leukemia." (PMID 36810516, 2023). "LINC00853 has been reported to regulate the level of CC chemokine receptor 9 (CCR9) modulating the binding of CCR9 and CC chemokine ligand 25 (CCL25), which was involved in the process of the infiltration of T cell acute lymphoblastic leukemia." (PMID 37403034, 2023).
type 1 diabetes (3 papers, 2018 to 2024). "Type-1 diabetes prone NOD mice harbor an increased number of IL-21-producing CCR9+ Th cells in the inflamed lesions of the pancreas and salivary glands that are phenotypically similar to Tfh cells." (PMID 30662436, 2018). "Astilbin decreased TNF-α and IFN-γ production and increased CCR9 expression of CD4+ T cells, and played a protective role in the onset of type 1 diabetes." (PMID 35652039, 2022).
allergic asthma (2 papers, 2020 to 2021). A asthma with a basis in a pathological type I hypersensitivity reaction. "In patients with allergic asthma, the CCR9/CCL25 binding method selectively induces chemotaxis of NKT cells, whereas in healthy volunteers, normal NKT cells are not able to induce." (PMID 34490243, 2021). "The CCR9/CCL25 axis has been shown to induce cellular recruitment in early allergic asthma." (PMID 33329590, 2020). "Additionally, we found increased expression of CCR9 and its receptor CCL25, which are involved in inflammatory cell recruitment in early allergic asthma." (PMID 33329590, 2020).
ankylosing spondylitis (2 papers, 2016 to 2024). An autoimmune chronic inflammatory disorder characterized by inflammation in the vertebral joints of the spine and sacroiliac joints. "KIR‐3DL2+CD4+ T cells in patients with ankylosing spondylitis were oligoclonal and enriched for markers of T cell activation and for the gut homing receptor CCR9." (PMID 26841353, 2016).
Arrhythmia (2 papers, 2016 to 2021). Any cardiac rhythm other than the normal sinus rhythm. "In conclusion, for the first time, this study shows that the loss of the CCR9 gene protected the mice from MI-induced inflammation, apoptosis, hypertrophy, fibrosis, and arrhythmia by regulating the NF-κB and MAPK pathways." (PMID 27585634, 2016). "It suggests CCR9 is a promising therapeutic target for MI-induced arrhythmia, which warrants further investigation." (PMID 34712704, 2021). "In this study, CCR9 abrogation was suggested to ameliorate MI-induced electrical remodeling by affecting ion current, AP, calcium homeostasis and cardiac conduction as well as gap junction, suggesting it may be a novel pharmaceutical target for the treatment of MI-induced arrhythmia." (PMID 34712704, 2021).
colonic disease (2 papers, 2016 to 2019). "When we compared CD patients with only ileal versus only colonic disease, we noted a significant decrease in circulating α4β7+CCR9+ subpopulations of mature NK and CD45RO+ NKT cells in ileal CD." (PMID 31217423, 2019). "In such a model, pro-inflammatory, effector mucosal CCR9+ T-cells would be preferentially recruited to the gut during the onset of active colonic disease in response to high levels of intestinal CCL25 expression." (PMID 26873648, 2016).
diabetes (2 papers, 2020). "We observed a significant decrease of diabetes incidence after IRT5 administration for 36 weeks, which was associated with reduced gut permeability and increased proportion of CCR9+ gut-tropic Treg cells." (PMID 33013834, 2020).
gastric cancer (2 papers, 2020 to 2025). A primary or metastatic malignant neoplasm involving the stomach. "PPI network analysis highlighted eight key hub genes (CD80, CCR9, CXCR3, CXCR5, CXCR6, CCR3, CCL20, and CXCL1), revealing their pivotal roles in gastric cancer and H. pylori infection." (PMID 40445003, 2025).
inflammatory liver diseases (2 papers, 2018 to 2022). "For example, CCR9/α4β7 and CCL25/MadCAM for gut homing, CXCR3 and CXCL9-11 for inflammatory liver diseases and specifically, CCR9, αEβ7, CCL25/E-cadherin in AISC and PSC." (PMID 30027532, 2018).
injury (2 papers, 2016 to 2022). Damage inflicted on the body as the direct or indirect result of an external force, with or without disruption of structural continuity. "Next, we examined the mechanisms underlying how CCR9+Mφs proliferate during the process of Con A-induced acute liver injury." (PMID 27725760, 2016). "In conclusion, the present study demonstrates that the inhibition of CCR9 in pDCs may augment their protective effect against acute liver injury by enhancing their migration to the diseased organ." (PMID 35943802, 2022).
pancreatic adenocarcinoma (2 papers, 2015 to 2022). "Furthermore, 92R decreases size of non-hematopoietic tumors with a forced CCR9 expression and of solid tumors generated by the pancreatic adenocarcinoma cell line AsPC-1." (PMID 35967322, 2022).
primary sclerosing cholangitis (2 papers, 2020 to 2022). "Gut-homing lymphocytes that express the integrin α4β7 and CCR9 might contribute to development of primary sclerosing cholangitis (PSC)." (PMID 31100458, 2020).
psoriasis (2 papers, 2016 to 2017). An autoimmune condition characterized by red, well-delineated plaques with silvery scales that are usually on the extensor surfaces and scalp. "Other researchers have shown that the upregulation of CCR9 was associated with a poor response to infliximab, which is an anti-tumor necrosis factor-α (TNF-α) antibody drug used in psoriasis patients." (PMID 26879872, 2016).
Rotavirus infection (2 papers, 2016 to 2025). Infection with any of the rotaviruses. "Similarly, there were more frequencies and cell numbers of intraepithelial Ly6A+CCR9+CD4+ T cells in small intestines from Trim29IEC-KO suckling mice than those from Trim29fl/fl mice after rotavirus infection for 3 days." (PMID 39396665, 2025). "Similarly, Toll like receptor 2 (TLR2) ligands have been shown to induce IgA and CCR9 expression in circulating B lymphocytes, and during the course of an acute rotavirus infection both IgA and IgM ASCs express CCR9 and are able to migrate to CCL25." (PMID 27003360, 2016).
Sepsis (2 papers, 2021). Sepsis is defined as life-threatening organ dysfunction caused by a dysregulated host response to infection. "Further, the proportion of γδ T cells expressing CCR9 was higher in the group of preterm neonates with a sepsis onset within the first 14 days of life." (PMID 34136218, 2021). "Moreover, paired analysis showed that the frequency of CCR9‐expressing γδ T cells clearly declined from day 14 to week 36 in the preterm infants regardless of sepsis." (PMID 34136218, 2021).
squamous cell carcinoma (2 papers, 2014 to 2025). A carcinoma arising from squamous epithelial cells. "Notably, CCR9 is more prevalent in adenocarcinomas than in squamous cell carcinomas, potentially explaining the former’s aggressive behavior and worse prognosis." (PMID 40607416, 2025). "Interestingly, expression of both CCR9 and CCL25 was significantly higher in adenocarcinomas (ACs) compared to squamous cell carcinomas (SCCs) (p = 0.04, and p < 0.0001)." (PMID 25296976, 2014). "Immunohistochemical analyses reveal consistent CCR9 overexpression in NSCLC tissues compared to adjacent non-tumorous and normal tissues, with particularly high levels observed in the squamous cell carcinoma line NCI-H157 relative to normal bronchial epithelial cells." (PMID 40607416, 2025).
T-cell leukemia (2 papers, 2012 to 2022). A malignant disease of the T-lymphocytes in the bone marrow, thymus, and/or blood. "92R mAb treatment of mice carrying human CCR9+ T-ALL cell lines or primary T cell leukemias inhibits tumor growth and increases survival." (PMID 35967322, 2022). "We next investigated the therapeutic effect of 92R mAb on primary human T-cell leukemia (HLPR, T-ALL18 and T-ALL10) expressing different CCR9 levels." (PMID 35967322, 2022). "Although these cells lacked the capacity to seed the thymus, probably because they do not express CCR7 and CCR9, they underwent malignant transformation upon constitutive activation of Notch signaling and gave rise to T cell leukemia." (PMID 22355330, 2012). "In addition, 92R mAb also increased survival in xenotransplanted animals carrying primary CCR9+ T cell leukemias and decreased the number of tumor-carrying animals, and their tumor size, on subcutaneous non-hematopoietic xenotransplants expressing CCR9." (PMID 35967322, 2022).
triple-negative breast carcinoma (2 papers, 2020 to 2025). An invasive breast carcinoma which is negative for expression of estrogen receptor (ER), progesterone receptor (PR), and human epidermal growth factor receptor 2 (HER2). "More interestingly, intratumoral delivery of CCL25 can enhance PD-L1/PD-1 antibody therapy against triple-negative breast cancer by recruiting CCR9+ T cells." (PMID 33034614, 2020). "Moreover, intratumoral delivery of CCL25 enhanced the response to immunotherapy in triple-negative breast cancer by recruiting CCR9+ T cells." (PMID 41042869, 2025).